MYO7A (myosin VIIA)
Diseases named in the same sentence as MYO7A in open-access papers (continued):
Sharing a sentence is not in itself a finding about the gene and the disease.
retinitis pigmentosa (28 papers, 2010 to 2026). Retinitis pigmentosa (RP) is an inherited retinal dystrophy leading to progressive loss of the photoreceptors and retinal pigment epithelium and resulting in blindness usually after several decades. "Pathogenic variants in MYO7A impair the function of these cells, leading to the profound sensorineural hearing loss seen in USH I. Additionally, MYO7A impairment affects photoreceptors, leading to retinitis pigmentosa and progressive visual loss." (PMID 40149483, 2025). "In a follow‐up study, the authors have reported the results of hybrid approach efficacy, pharmacokinetics and safety in mice and primates injected with AAV8.MYO7A dual hybrid vector for the treatment of retinitis pigmentosa associated with USH1B." (PMID 38488469, 2024). "One case with a novel MYO7A variant showed a milder phenotype with progressive hearing loss and late-onset retinitis pigmentosa." (PMID 34824372, 2022). "MYO7A: NM_000260:c.1667G>T:p.G556V was previously reported as a causative variant for retinitis pigmentosa and other is the novel variant MYO7A: NM_000260:c.1369G>A:p.A457T." (PMID 34824372, 2022). "After evaluating with this test, 16 known variants were detected in 16 individuals in whom four showed retinitis pigmentosa (RP) and hearing loss with homozygous and compound heterozygous variants in MYO7A, CDH23 and USH2A genes." (PMID 31850270, 2019). "Four patients had retinitis pigmentosa (RP) with HL in three causative genes, MYO7A, CDH23 and USH2A, with novel and known variants." (PMID 31850270, 2019). "This has important implications, because mutations in MYO7A cause Usher syndrome 1B—an autosomal recessive disorder characterized by bilateral sensorineural hearing loss and blindness due to retinitis pigmentosa." (PMID 26960254, 2016). "In SRP1400-II:1, a de novo HK1 variant caused retinitis pigmentosa (RP)-like retinal degeneration and intellectual disability and in USHI105-II:1, MYO7A variants primarily resulted in an Usher syndrome 1 phenotype." (PMID 40269797, 2025). "In particular, all the Usher patients (i.e., patients displaying HL and retinitis pigmentosa) were molecularly characterized, identifying homozygous or compound heterozygous mutations in USH2A and MYO7A genes." (PMID 33105617, 2020). "Mutations in MYO7A cause autosomal recessive Usher syndrome type IB (USH1B), one of the most frequent conditions that combine severe congenital hearing impairment and retinitis pigmentosa." (PMID 23991031, 2013). "Mutations in MYO7A, USH1C, CDH23, PCDH15 and WHRN have also been reported in patients affected by hearing impairment only, while USH2A is also involved in isolated retinitis pigmentosa." (PMID 21569298, 2011). "Among them, MYO7A mutation causes nonsyndromic hearing loss DFNA11 (OMIM #601317), DFNB2 (OMIM #600060), and syndromic hearing loss Usher syndrome type 1 B (USH1B, OMIM #276900), characterized by sensorineural hearing loss, retinitis pigmentosa, and variable vestibular areflexia." (PMID 35453549, 2022). "Syndromic MYO7A mutations are inherited in a recessive manner, leading to a diagnosis of Usher type 1B (USH1B), which is the most severe, and characterized by congenital profound hearing loss, prepuberal onset of retinitis pigmentosa, and vestibular dysfunction." (PMID 28472130, 2017).
retinal degeneration (16 papers, 2013 to 2025). Degeneration of the retina. "The mutant phenotypes in the retinas of Myo7a mutant mice suggest deficiencies in the overall turnover of outer segment disc membranes as a mechanism underlying retinal degeneration in the Usher 1B subgroup." (PMID 37762059, 2023). "Myosin VIIa is of particular interest since mutations in the MYO7A gene cause Usher syndrome 1B which involves progressive retinal degeneration." (PMID 33281830, 2020). "Q-PCR analyses showed J cybrids had decreased expressions for CFH, C3, and EFEMP1 genes, high risk genes for AMD, and higher expression for MYO7A, a gene associated with retinal degeneration in Usher type IB syndrome." (PMID 23365660, 2013). "This suggests that cataract may not only be age-related or secondary to retinal degeneration but may also be influenced by the molecular mechanisms associated with MYO7A dysfunction." (PMID 40725401, 2025). "The MYO7A gene is expressed in the RPE and photoreceptor cells, and has been associated with the retinal degeneration found in Usher syndrome type IB." (PMID 23365660, 2013). "Moreover, in the era of emerging retinal therapies, gene augmentation strategies for MYO7A retinal degeneration have proved to be successful in treating animal models." (PMID 38884554, 2024). "In addition, a young patient with pde6b and myo7a gene mutations (underlying USH1B) presented earlier and more sever retinal degeneration than his older siblings with a homozygous pde6b mutation." (PMID 27186975, 2016). "This stress response may be a primary factor in retinal degeneration caused by mutations in MYO7A, but upregulation of apoptotic pathways may indicate that Muller and bipolar cells should be further investigated for their role in USH1B pathophysiology." (PMID 40620763, 2025). "Like previously examined mouse models, we show that Myo7a–/– do not exhibit retinal degeneration and have only marginal decrements in retinal function." (PMID 31824252, 2019). "Mice potentially lack calyceal processes and do not exhibit retinal degeneration in the absence of MYO7A." (PMID 31824252, 2019). "However, unlike PMEL, both myosin VIIa and Rep1 are also expressed in the photoreceptors and so trafficking defects within the photoreceptors, as well as in the RPE, contribute to the observed retinal degeneration." (PMID 25690007, 2015).
Blindness (12 papers, 2014 to 2025). Blindness is the condition of lacking visual perception defined as a profound reduction in visual perception. "Mutations in Myo7a are associated with the Usher syndrome I, a genetically heterogeneous condition that is characterized by congenital sensorineural deafness, absent vestibular function and prepubertal onset of progressive retinitis pigmentosa leading to blindness." (PMID 35269767, 2022). "Most individuals with MYO7A-related USH1 experience total blindness by their 20s and have severe delays in motor development due to vestibular dysfunction combined with visual impairment." (PMID 40149483, 2025). "In one study, 50% of MYO7A patients reached legal blindness based on either VF < 20° or BCVA ≤ 0.1 at 41 years of age, whereas in comparison, 50% of the p.Cys870* USH2A patients in the present study experienced the same visual loss at 50 years of age." (PMID 36980924, 2023). "Loss of functional myosin VIIa in the retinal pigment epithelia (RPE) and/or photoreceptors leads to blindness." (PMID 24705452, 2014).
nonsyndromic hearing loss (9 papers, 2014 to 2024). "MYO7A is also associated with nonsyndromic hearing loss (DFNB2, DFNA11)." (PMID 30123251, 2018). "The other two myosin genes, MYO6 and MYO7A, depending on the variants, are associated with both autosomal dominant and recessive nonsyndromic hearing loss, respectively, as DFNA22 and DFNB37 for MYO6 and DFNA11 and DFNB2 for MYO7A." (PMID 38562617, 2024). "MYO7A encodes an unconventional myosin, myosin VIIA, which, when mutated, causes a phenotypic spectrum ranging from recessive nonsyndromic hearing loss (DFNB2) to syndromic deaf-blindness, Usher Type 1B (USH1B)." (PMID 33671976, 2021). "In some cases, different variants in the same gene, such as MYO7A, may result in distinct phenotypes in nonsyndromic deafness DFNA11 and DFNB2 or syndromic deafness USH1B." (PMID 33976695, 2021).
autosomal recessive hearing loss (8 papers, 2013 to 2023). "Fourteen variants causing autosomal dominant deafness were clustered in motor and MyTH4 domains of MYO7A protein." (PMID 35453549, 2022). "Members of the myosin superfamily (MYO7A, MYO15A, and MYO6) are involved in voice conduction, but variants in MYO15A are now considered to be one of the most common causes of nonsyndromic autosomal recessive hearing loss (ARNSHL)." (PMID 31250571, 2019). "In particular, we did not test the most frequently mutated genes in patients with autosomal recessive hearing loss, such as SLC26A4, USH2A, and MYO7A, because their large size would have made Sanger sequencing labour-intensive." (PMID 30344259, 2018).
Retinal dystrophy (6 papers, 2021 to 2025). Retinal dystrophy is an abnormality of the retina associated with a hereditary process. "We investigated the natural history of retinal dystrophy owing to variants in the MYO7A gene." (PMID 38884554, 2024). "In addition, the reported variants were of clinical significance as the PDE6C variant was detected novel, whereas TULP1, MERTK, and MYO7A variants were detected rare and first time found segregating with retinal dystrophies in Pakistani consanguineous families." (PMID 37165311, 2023). "Further, three genes, ABCA4, MYO7A and NR2E3, are shown to have an association to PRC thickness and have a prior association with retinal dystrophies." (PMID 36848389, 2023).
Stargardt disease (6 papers, 2014 to 2025). "Other viral vectors such as lentiviral vectors have been used for some autosomal recessive disorder to deliver cDNA copies of the mutant genes that are too large to be carried by AAV, e.g., ABCA4 gene associated with Stargardt disease and MYO7A associated with Usher’s syndrome." (PMID 35911417, 2022). "Forty Clinically important genes that are larger in size like ABCA4 and MYO7A for Stargardt disease and USH1B, respectively, can be packaged into EIAV." (PMID 35911417, 2022). "Two genes that do not fit in a conventional rAAV gene cassette (MYO7A linked to Usher syndrome Type 1B and ABCA4 to Stargardt disease) have been delivered to the retina by recombinant lentiviral expression vectors instead." (PMID 32545533, 2020).
myopia (5 papers, 2020 to 2025). "This was initially felt to be related to high myopia OU and keratoconus OU; however, the ffERG was abnormal OU as well, which prompted genetic testing revealing a MYO7A variant, which is associated with autosomal recessive Usher type 1." (PMID 34603194, 2021). "Interestingly, (high) hyperopia (MFRP, MYO7A, BEST1) was more common in this group than myopia." (PMID 41465105, 2025).
sensorineural hearing loss (5 papers, 2014 to 2023). "Among the 300 families with sensorineural hearing loss after the first decade of life in the YUHL cohort, we detected 12 heterozygous missense variants of MYO7A in 14 unrelated families." (PMID 35453549, 2022).
melanoma (3 papers, 2022 to 2024). A malignant, usually aggressive tumor composed of atypical, neoplastic melanocytes. "In an analysis using IPA software, MYO7A was associated with melanoma, cancer, and melanosome degradation and localization." (PMID 35085295, 2022). "Moreover, another MYO7A variant (rs2276288) was associated with increased melanoma susceptibility." (PMID 35085295, 2022). "Transcripts related to melanoma progression and poor prognosis (Sox6, Sox11, Tfap2a, Myo7a) were upregulated in IgG-treated animals." (PMID 38740748, 2024). "From our list of prioritized variants and genes, three genes (MYO7A, WRN and NOP10) warrant a more detailed discussion, due to gene function and previous associations with melanoma." (PMID 35085295, 2022). "This is notably the case for some melanoma models, in which the overexpression of the USH1B/MYO7A protein facilitates their progression, which may be a link to cancer proneness." (PMID 35163494, 2022).
retinal disease (3 papers, 2014 to 2021). "Differences in retinal disease presentation across species are likely related to differential expression of MYO7A in mouse vs. primate retina." (PMID 31824252, 2019).
Usher syndrome type 2 (3 papers, 2019 to 2025). A syndrome characterized by congenital, bilateral sensorineural hearing loss that is mild to moderate in the low frequencies and severe to profound in the higher frequencies, no abnormalities in the vestibular system, and retinitis pigmentosa. "Although rare, a MYO7A variant also correlated with Usher syndrome type 2, which presents less severe features than type 1B." (PMID 40852359, 2025).
autism (2 papers, 2024 to 2025). Persistent deficits in social interaction and communication and interaction as well as a markedly restricted repertoire of activity and interest as well as repetitive patterns of behavior. "CNTNAP2 has previously been linked to autism and intellectual disability, BRAF to epilepsy, TRANK1 to schizophrenia, and LRPPRC/MYO7A to mitochondrial and ciliary disorders." (PMID 40282380, 2025).
lung carcinoma (2 papers, 2019 to 2022). "Two mRNAs (Myo7a and Zfp874a) and two lncRNAs (n290048 and n271850) were highlighted as the most important genes and lncRNAs for spontaneous lung cancer susceptibility prediction." (PMID 30719228, 2019). "After GWA filtration, two mRNAs (Myo7a and Zfp874a) and two lncRNAs (n290048 and n271850) were highlighted as the candidates responsible for genetic susceptibility to lung cancer." (PMID 30719228, 2019). "No direct association between Myo7a and lung cancer is found." (PMID 30719228, 2019).
night blindness (2 papers, 2025). Inability to see clearly in dim light. "MYO7A-related USH I typically leads to early onset of night blindness and a rapid progression of visual field constriction, eventually leading to severe impairment or loss of visual acuity." (PMID 40149483, 2025).
autosomal recessive rod-cone dystrophy (1 paper, 2025). "Moreover, MYO7A can cause autosomal recessive rod-cone dystrophy in the retina, which may explain why the two patients with fluctuation CME exhibited abnormalities and phenotypic characteristics of rod-cone dysfunction." (PMID 40852359, 2025).
Bardet-Biedl syndrome (1 paper, 2020). A ciliopathy with multisystem involvement. "Patient RP_37 showed causative homozygous variants in genes related to Usher Syndrome (MYO7A) and Bardet-Biedl Syndrome (BBS2)." (PMID 33374679, 2020).
choroideremia (1 paper, 2022). Choroideremia (CHM) is an X-linked chorioretinal dystrophy characterized by progressive degeneration of the choroid, retinal pigment epithelium (RPE) and retina. "Several monogenic forms of retinal degeneration are also caused by mutations in genes that are expressed in the RPE; for example, mutations in MERTK, which cause retinitis pigmentosa, CHM, which cause choroideremia, and MYO7A which cause Usher syndrome type 1B." (PMID 35309899, 2022).
cyst (1 paper, 2025). A sac-like closed membranous structure that may be empty or contain fluid or amorphous material. "These authors suggest that the localization pattern confirms accumulation of myosin VIIA in the ring canals–cytoplasmic bridges connecting germline cyst cells." (PMID 40530337, 2025).
dementia (1 paper, 2025). Loss of intellectual abilities interfering with an individual's social and occupational functions. "Other genes previously associated with AD or dementia were differentially expressed in both brain regions: CHI3L2, FCGBP, GLI1, STAB1, APOC1, MYO7A, and long non‐coding RNA JHDM1D‐AS1." (PMID 39876821, 2025).
Griscelli syndrome (1 paper, 2014). Griscelli syndrome (GS) is characterized by silvery gray sheen of the hair and hypopigmentation of the skin which can be associated to neurological impairment (type 1), immunodeficiency (type 2) or be isolated (type 3). "While Myo5a phenocopied human Griscelli syndrome, a role for Myo7a in epidermal pigmentation was not predicted." (PMID 24721909, 2014).
Hydrocephalus (1 paper, 2023). Hydrocephalus is an active distension of the ventricular system of the brain resulting from inadequate passage of CSF from its point of production within the cerebral ventricles to its point of absorption into the systemic circulation. "INPH-associated mutations identified in this study affected two other genes, MYO7A and SPG11, that have previously been shown to cause hydrocephalus or ventriculomegaly." (PMID 38100419, 2023).
Meniere disease (1 paper, 2022). A disease of the inner ear (labyrinth) that is characterized by fluctuating sensorineural hearing loss; tinnitus; episodic vertigo; and aural fullness. "New studies report that the hearing loss profile does not only affect the low frequency in the early stages; however, a flat sensorineural hearing loss was observed in patients with familial Meniere’s disease and mutations in OTOG and MYO7A." (PMID 35683514, 2022).
presbycusis (1 paper, 2019). Bilateral hearing loss caused by progressive degeneration of cochlear structures and central auditory pathways, typically associated with the aging process. "Instead, Myo7a+/– mice display characteristics of early onset age-related hearing loss which, in its early stages, typically manifests as a loss of threshold sensitivity at higher frequencies and a loss of outer HCs in the basal cochlea." (PMID 31824252, 2019). "The loss of high-frequency ABR thresholds and basal cochlear HCs we observed in 5-month-old Myo7a+/– mice appear to mimic the early stages of presbycusis." (PMID 31824252, 2019).
retinal ciliopathies (1 paper, 2024). "This review will discuss the state of hiPSC-derived retinal organoid technology for accurately modelling prominent retinal ciliopathies related to genes, including RPGR, CEP290, MYO7A, and USH2A." (PMID 38474133, 2024).
Strabismus (1 paper, 2025). A misalignment of the eyes so that the visual axes deviate from bifoveal fixation. "Analysis also revealed a statistically significant association between MYO7A mutations and both cataract (p = 0.041) and strabismus (p = 0.013)." (PMID 40725401, 2025).